GDPD2 (glycerophosphodiester phosphodiesterase domain containing 2)
Description:
Calcium-dependent ecto-phospholipase C that cleaves the phosphodiester bond between the glycerol backbone and phosphate group of glycerophospholipids at the cell surface, regulating multiple signaling pathways. Substrates include GPI-anchored proteins, which are released from the membrane upon cleavage of the inositol-phosphate linkage. For example, cleavage and release of UPAR/PLAUR regulates cell-matrix adhesion and extracellular matrix remodeling. Also cleaves the glycosylphosphatidylinositol (GPI) anchor of metalloproteases TRABD2A and TRABD2B, releasing them from the plasma membrane. This release modulates their regulation of Wnt signaling. Also hydrolyzes lysophosphatidylinositol (LPI) to monoacylglycerol and inositol-1-phosphate. Converts 2-arachidonoyl-LPI, the endogenous GPR55 agonist, into 2-arachidonoylglycerol (2-AG), an endocannabinoid that activates CNR1/CNR2. Thereby, acts as a switch redirecting signaling from GPR55 to CNR1/CNR2 within the endocannabinoid system that could alternatively regulate osteoblast proliferation and differentiation. Can also cleave glycerophosphoinositol to glycerol and inositol-1-phosphate in vitro (By similarity). May also play a role in remodeling of the actin cytoskeleton (By similarity).
Synonyms: GDE3; OBDPF; FLJ20207
Tractability: Antibody: UniProt places it where antibodies can reach, with medium confidence; UniProt predicts a signal peptide or a membrane-spanning region; its Gene Ontology location is reachable by antibodies, with medium confidence. PROTAC: its protein half-life has been measured.
Gene: Protein-coding gene on chromosome X (70,423,031 to 70,433,710, forward strand). Ensembl gene ENSG00000130055.
Subcellular location: Cell membrane
Gene Ontology:
Molecular function: phospholipase C activity; glycerophosphodiester phosphodiesterase activity; glycerophosphoinositol inositolphosphodiesterase activity; phosphoric diester hydrolase activity
Biological process: negative regulation of cell-matrix adhesion; negative regulation of extracellular matrix disassembly; negative regulation of oligodendrocyte progenitor proliferation; protein maturation; negative regulation of osteoblast proliferation; positive regulation of osteoblast differentiation; lipid metabolic process
Cellular component: plasma membrane; actin filament; lamellipodium
Homologues: Orthologues: chimpanzee GDPD2 (100% identical), macaque GDPD2 (90% identical), mouse Gdpd2 (85% identical), pig GDPD2 (85% identical), rabbit GDPD2 (83% identical), guinea pig GDPD2 (81% identical), rat Gdpd2 (79% identical), dog GDPD2 (79% identical), tropical clawed frog gdpd2 (45% identical), zebrafish gdpd2 (39% identical). Paralogues in human: GDPD5 (42% identical), GDPD4 (33% identical), GDE1 (12% identical), GDPD1 (11% identical), GDPD3 (9% identical).
Diseases named in the same sentence as GDPD2 in open-access papers:
GDPD2 is named in the same sentence as 6 diseases in open-access papers, as found by Europe PMC text mining. Sharing a sentence is not in itself a finding about the gene and the disease. The quoted sentences say what the papers report.
asthma (2 papers, 2018 to 2023). "In this study, several genes including Gdpd2, Spon2, Pon1, Scgb3a2, Ighv2-3, Sult1d1, Cyp2f2, Npas2, Arntl, and Igkv4-68 were down-regulated in OVA-challenged mice compared with control mice, may be useful as biomarkers of asthma." (PMID 29086354, 2018).
breast carcinoma (1 paper, 2017). "Expression of GDE3 (encoded by GDPD2) is relatively low in breast cancer lines (n = 51), including MDA-MB-231 cells." (PMID 28849762, 2017). "Finally, in patients, high expression of GDPD2 was found to correlate with prolonged relapse-free survival in breast cancer, particularly in triple-negative (basal-like) subtype patients (N = 618)." (PMID 28849762, 2017).
GDPD2 also shares sentences with these, for which no sentence is quoted: tumor (2 papers); cancer (1); Intellectual disability (1); triple-negative breast carcinoma (1).